DUOX1 (dual oxidase 1)
Diseases named in the same sentence as DUOX1 in open-access papers (continued):
Sharing a sentence is not in itself a finding about the gene and the disease.
influenza (4 papers, 2016 to 2023). An acute viral infection of the respiratory tract, occurring in isolated cases, in epidemics, or in pandemics; it is caused by serologically different strains of viruses (influenzaviruses) designated A, B, and C, has a 3-day incubation period, and usually lasts for 3 to 10 days. "Furthermore, Aqp3–/– and Duox1–/– mice had decreased leukocyte recruitment in models of allergic asthma, and Duox1–/– mice have increased susceptibility to influenza." (PMID 36166305, 2022). "Previously, we showed a similar trend in an influenza infection model where the Duox1 KO lung tissues (likely airway epithelium) showed higher levels of the same apoptotic marker." (PMID 36936954, 2023). "We have recently shown the relevance of Duox1 in antiviral innate immunity in a murine model of influenza infection." (PMID 36936954, 2023). "We have previously shown that DUOX1 has an important role in antiviral immunity in vivo by improving airway epithelial influenza viral clearance, shaping the early antiviral innate response, and reducing infection-related morbidity and mortality." (PMID 36936954, 2023). "In contrast, our prior influenza study in Duox1 KO mice used 19-20 mice per group for cytokine measurements." (PMID 36936954, 2023). "Only FAM157A, leucine-rich alpha 2 glycoprotein, serum amyloid A protein, and dual oxidase 1 were statistically significantly different in plasma of healthy versus influenza-infected individuals by LC-MS." (PMID 27088501, 2016). "Duox1–/– mice have increased morbidity and mortality when influenza challenged." (PMID 36166305, 2022). "Indeed, DUOX1 was recently demonstrated to possess antiviral properties against influenza in mice, which was related to H2O2-dependent production of hypothiocyanite (OSCN−) by lactoperoxidase in airway epithelial secretions." (PMID 34829671, 2021). "Unlike in the case of our data here on Mtb, Duox1 affected viral proliferation in the lungs of influenza-infected mice suggesting that Duox1 could play a pathogen-specific role in regulating apoptosis and general respiratory innate immunity." (PMID 36936954, 2023).
thyroid disease (4 papers, 2019 to 2024). "Concerning thyroid malignancies, elevated DUOX1 mRNA levels were reported in papillary thyroid carcinomas (PTC) and follicular adenomas of patients with a history of childhood radiation." (PMID 31083324, 2019). "Nicotinamide adenine dinucleotide phosphate (NADPH) oxidases (Dual oxidase 1, Dual oxidase 2, NADPH oxidase 4) are expressed in the human thyroid gland and function as sources of ROS, suggesting that they may play a role in the pathogenesis of thyroid diseases." (PMID 36326389, 2022).
allergic asthma (3 papers, 2015 to 2023). A asthma with a basis in a pathological type I hypersensitivity reaction. "A previous study has demonstrated that Duox1 is required for neutrophil recruitment in a mouse model of allergic asthma." (PMID 36936954, 2023).
Allergy (3 papers, 2015 to 2024). An allergy is an immune response or reaction to substances that are usually not harmful. "DUOX1‐dependent phosphorylation of Src and EGFR in mice exposed to Alternaria extract demonstrates a similar role for DUOX1 in fungal‐induced allergy." (PMID 37357550, 2023).
chronic obstructive pulmonary disease (3 papers, 2018 to 2024). A chronic and progressive lung disorder characterized by the loss of elasticity of the bronchial tree and the air sacs, destruction of the air sacs wall, thickening of the bronchial wall, and mucous accumulation in the bronchial tree. "Patients with chronic obstructive pulmonary disease (COPD) have increased the susceptibility to HRV and HRV-infected airway epithelial cells from COPD patients show elevated levels of Duox1 and Duox2." (PMID 30049972, 2018). "However, our findings are in line with previous reports of a positive correlation between another AMP, such as dual oxidase 1 (DUOX1), and better spirometry and DLCO in chronic obstructive pulmonary disease (COPD) patients." (PMID 38673881, 2024).
fungal infection (3 papers, 2013 to 2022). "Interestingly, low expression (less than two-fold) of DUOX1, PRXS1L and TXNL1 was observed upon fungal infection among winged imagoes, nymphs, soldiers and workers." (PMID 29231889, 2017).
gastric cancer (3 papers, 2019 to 2021). A primary or metastatic malignant neoplasm involving the stomach. "In gastric cancer, mRNA expression of DUOX1 was downregulated, whereas, high levels of DUOX1 mRNA were correlated with poor prognosis, paradoxically." (PMID 31706280, 2019). "Curiously, gastric cancer showed inverse relationship for CDCA5, CRNN and DUOX1 on prognosis compared to other cancer types (red asterisks)." (PMID 31443700, 2019). "Similarly, several studies over a large number of patients suffering from gastric cancers (GC) also showed that high levels of NOX2/4, and DUOX1 at the tumor site, compared to adjacent tissues, constitute reliable prognostic markers in GC." (PMID 34205998, 2021). "Interestingly, gastric cancer showed inverse relationship for CDCA5, CRNN and DUOX1 on prognosis compared to other cancer types investigated." (PMID 31443700, 2019).
metastatic cancer (3 papers, 2016 to 2026). A carcinoma which has spread from the original site of growth to another anatomic site. "Epithelial-mesenchymal transition (EMT) is a key feature of aggressive and metastatic cancers, and the loss of DUOX1 is associated with a decrease in the epithelial marker E-cadherin, indicating that DUOX1 is closely associated with EMT." (PMID 41556052, 2026).
ovarian carcinoma (3 papers, 2017 to 2021). A malignant neoplasm originating from the surface ovarian epithelium. "It has been reported that ovarian cancer cells that express high levels of Duox1 and high levels of activated Chk1 are relatively Cisplatin-resistant." (PMID 34622778, 2021). "Meanwhile, we constructed a novel prognostic signature consisting of three FRGs (HIC1, LPCAT3, DUOX1), The three FRG-based risk score model was capable of distinguishing ovarian cancer patients with significantly different outcomes, and the risk score was the independent prognostic factor." (PMID 35071242, 2021).
cervical squamous cell carcinoma (2 papers, 2019 to 2020). A squamous cell carcinoma arising from the cervical epithelium. "The protein expression of DUOX1, DUOX2, and NOX2 also identified in cervical squamous cell carcinoma tissues." (PMID 31706280, 2019). "In addition, mRNA and protein levels of DUOX1 and DUOX2 were higher in patients with cervical squamous cell carcinoma than in those with endocervical adenocarcinoma." (PMID 31706280, 2019). "DUOX1 and DUOX2 protein expression were also identified in cervical squamous cell carcinoma." (PMID 31706280, 2019).
Coccidioides infection (2 papers, 2022 to 2024). "Mutations in DUOX1 or DUOX1A were also more common in patients with disseminated coccidioidomycosis than controls." (PMID 38535182, 2024). "Recently, Hsu reported that mutations in Duox1, a lung epithelial cell oxidase that generates H2O2, were more common in patients with disseminated coccidioidomycosis than in the general population, suggesting that this enzyme plays a role in innate resistance to coccidioidomycosis." (PMID 38535182, 2024).
colitis (2 papers, 2022 to 2023). Inflammation of the colon. "Furthermore, Duox2∆IEC mice with a specific deletion of DUOX2 in the intestinal mucosa were protected from acute experimental colitis, unlike Duoxa−/− mice with systemic inactivation of DUOX1 and DUOX2, which did not display an altered susceptibility to experimental colitis." (PMID 37891968, 2023).
colon cancer (2 papers, 2010 to 2013). "Among the group of the most consistently hypermethylated genes in both human colon cancer and mouse intestinal adenoma (48 genes), we found Cdh4, Crabp1, Crmp1, Dbc1, Duox1, Grm7, Hand1, Hs3st2, Pcdh17 and Pdpn, which have previously been suggested as cancer biomarkers." (PMID 23408899, 2013).
fibrosis (2 papers, 2019 to 2021). the formation of excess fibrous connective tissue in an organ or tissue in a reparative or reactive process. "Finally, development of subepithelial airway fibrosis in mice due to exposure to the CS-component acrolein, or alveolar emphysema induced by administration of elastase, were in both cases exacerbated in Duox1-deficient mice." (PMID 33301419, 2021). "In the lung, it has been shown that some pro-oxidant enzymes such as NADPH oxidase-1 (NOX1), NOX2, NOX4, as well as Duox1 and Duox2 are involved in oxidative stress and development of fibrosis." (PMID 31366142, 2019).
gastritis (2 papers, 2017 to 2019). Inflammation of the stomach. "Among other NOX family members, expression of Nox2, Duox1 and Duox2 was increased significantly in mouse gastric tumors; however, only Duox2 showed gastritis-associated induction." (PMID 30700829, 2019).
lung adenocarcinoma (2 papers, 2016 to 2026). A carcinoma that arises from the lung and is characterized by the presence of malignant glandular epithelial cells. "Based on the multivariate analysis, we constructed a prognostic nomogram to predict the prognosis of patients with lung adenocarcinoma based on DUOX1 expression and other independent clinical variables." (PMID 41556052, 2026). "DUOX1 mRNA expression was decreased in all stages and pathological subtypes of lung adenocarcinoma (P < 0.05)." (PMID 41556052, 2026). "Based on the TCGA database, the transcriptional levels of DUOX1 in 59 normal lung tissues and 516 primary tumor tissues of patients with lung adenocarcinomas were detected." (PMID 41556052, 2026). "We found that DUOX1 was lowly expressed in lung adenocarcinomas, and its expression level was lower in micropapillary and solid lung adenocarcinomas than in other subtypes." (PMID 41556052, 2026). "In this study, TCGA was used to further verify the expression pattern and clinical significance of DUOX1 mRNA in lung adenocarcinoma." (PMID 41556052, 2026). "In this study, Spearman correlation was used to show the relationship between DUOX1 mRNA and the level of immune cell infiltration in lung adenocarcinoma." (PMID 41556052, 2026). "This study aimed to evaluate the correlation between DUOX1 mRNA expression and the prognosis of patients with lung adenocarcinoma." (PMID 41556052, 2026). "The expression level of DUOX1 was decreased in different histological types of lung adenocarcinoma (P < 0.05) and was lower in micropapillary and solid lung adenocarcinoma than in other subtypes." (PMID 41556052, 2026). "Furthermore, based on the TCGA database, we analyzed the biological behavior and clinical significance of DUOX1 in lung adenocarcinoma using bioinformatics technology." (PMID 41556052, 2026). "Therefore, we developed a predictive nomogram model combining clinicopathological variables and DUOX1 mRNA to predict the survival of patients with lung adenocarcinoma." (PMID 41556052, 2026). "Multivariate COX regression analysis further showed that DUOX1 low expression did not significantly increase the survival risk of patients with lung adenocarcinoma (P > 0.05)." (PMID 41556052, 2026). "Furthermore, the expression level of DUOX1 was decreased in different histological subtypes of lung adenocarcinoma and was lower in micropapillary and solid lung adenocarcinoma than in other subtypes." (PMID 41556052, 2026). "Furthermore, we developed a predictive nomogram model combining clinicopathological variables and DUOX1 mRNA to predict the survival of patients with lung adenocarcinoma." (PMID 41556052, 2026). "Univariate and multivariate Cox regression analysis also suggested that DUOX1 was associated with the prognosis of patients with lung adenocarcinoma, but it could not be used as an independent and reliable predictor." (PMID 41556052, 2026). "Furthermore, the low expression of DUOX1 occurs at all stages of lung adenocarcinoma, suggesting that the silencing of DUOX1 may promote the progression of SP-LUAD." (PMID 41556052, 2026). "In addition, although we analyzed the biological function and clinical significance of DUOX1 in lung adenocarcinoma, it has not been experimentally verified." (PMID 41556052, 2026).
lung fibrosis (2 papers, 2023 to 2024). "For example, in lung fibroblasts, DUOX1-derived H2O2 amplified the signaling output of the TGF-β1 pathway and exacerbated bleomycin-induced lung fibrosis." (PMID 37923730, 2023).
melanoma (2 papers, 2013 to 2023). A malignant, usually aggressive tumor composed of atypical, neoplastic melanocytes. "As this effect is only observed in immunocompromised individuals, the immune system appears to be able to counteract this elevated metastatic potential of DUOX1-deficient melanomas." (PMID 36978957, 2023). "It was found that high transcript levels of the gene encoding DUOX1 were associated with the poor prognosis of patients in the early-stage melanoma of TCGA cohort." (PMID 36978957, 2023). "Our results confirmed a dual role of DUOX1, which restrains melanoma proliferation but promotes metastasis." (PMID 36978957, 2023). "In the present study, we used these zebrafish models of melanoma to address the role of DUOX1 in the aggressiveness of melanoma cells in vivo." (PMID 36978957, 2023). "Using zebrafish primary melanoma and allotransplantation models, we interrogated the role of DUOX1 in vivo." (PMID 36978957, 2023). "The relevance of this enzyme in melanoma was further confirmed by our analysis of the SKCM patient cohort of TCGA that showed that high transcript levels of DUOX1 were associated with poor survival of early-stage but not of late-stage SKCM patients." (PMID 36978957, 2023). "However, our recent studies have shown using real time RT-PCR that Duox1 is only minimally expressed at the mRNA level, and clearly not upregulated, in many human malignancies, including cancers of the gastrointestinal tract, breast, lung, prostate, brain and melanoma." (PMID 23404210, 2013).
prostate carcinoma (2 papers, 2017 to 2022). A carcinoma that arises from epithelial cells of the prostate gland. "There is a report that ROS levels in prostate cancer (PC-3 cells) are constitutively maintained by DUOX1 and 2, and these ROS lead to increased apoptosis resistance via positive regulation of Akt signaling." (PMID 29065504, 2017). "Three genes (CD177, DUOX1, and AOC1) were downregulated in prostate cancer through the analysis of bioinformatics data; the roles of both CD177 and DUOX1 in prostate cancer have been reported." (PMID 35922412, 2022). "The roles of CD177 and DUOX1 in prostate cancer have been comprehensively reported; however, how AOC1 is involved in prostate cancer remains unclear." (PMID 35922412, 2022). "On the other hand, it has been reported that DUOX1 mRNA expression in prostate cancer tissues is significantly lower than that in non-tumor tissues." (PMID 29065504, 2017). "Thus, although DUOX1 expression has been detected in prostate cancer cells, its pathological significance is not fully understood." (PMID 29065504, 2017).
autoimmune thyroid disease (1 paper, 2018). Inflammatory disease of the thyroid gland due to autoimmune responses leading to lymphocytic infiltration of the gland. "Upregulation of DUOX1 expression can also underlie or contribute to autoimmune thyroid diseases." (PMID 30558263, 2018).
breast tumor (1 paper, 2018). "Interestingly, we observed a lower DUOX1 expression in breast tumor cells and tumor tissues in comparison to its control." (PMID 29849884, 2018). "Based on this, we hypothesized that in normal condition, DUOX1 could be involved in IL-6 and IL-8 secretion after genotoxic stress in mammary epithelial cells; however, the physiological relevance of the lower DUOX1 expression found in breast tumor remains to be elucidated." (PMID 29849884, 2018). "The levels of DUOX1 expression does not seem to correlate with tumor prognosis, because the triple negative cell line MDA-MB-231 presented the same levels of DUOX1 mRNA than the ER-positive breast tumor cell MCF7." (PMID 29849884, 2018).
experimental autoimmune encephalomyelitis (1 paper, 2016). An autoimmune demyelinating disease of the central nervous system that is produced experimentally in animals by the injection of homogenized brain or spinal cord in Freund's adjuvant. "Here, we employ intravital NAD(P)H fluorescence lifetime imaging to detect functional NADPH oxidases (NOX1–4, DUOX1, 2) and, thus, to identify the cellular source of oxidative stress in the CNS of mice affected by experimental autoimmune encephalomyelitis (EAE) in the remission phase of the disease." (PMID 27014271, 2016).
Fanconi anemia (1 paper, 2021). Fanconi anemia (FA) is a hereditary DNA repair disorder characterized by progressive pancytopenia with bone marrow failure, variable congenital malformations and predisposition to develop hematological or solid tumors. "Among them, cysteine dioxygenase 1 (CDO1), toll-like receptor 4 (TLR4), and dual oxidase 1 (DUOX1) were downregulated in tumors and played a protective role, while Fanconi anemia complementation group D2 (FANCD2) and others were with high expression in tumors and were risk factors for prognosis." (PMID 34820377, 2021).
goiter (1 paper, 2019). Enlargement of the thyroid gland usually caused by lack of iodine in the diet, hyperthyroidism, or thyroid nodules. "Patients and Methods: Forty-three children with CH with goiter were enrolled, in whom all exons and flanking intronic regions of DUOX1/DUOXA1 were directly sequenced." (PMID 31428054, 2019).
H1N1 influenza (1 paper, 2023). "A similar, overall role of Duox1 in shaping the early cytokine environment of the airways was established in our prior study using an H1N1 influenza strain." (PMID 36936954, 2023).